AQP1 (aquaporin 1 (Colton blood group))
Diseases named in the same sentence as AQP1 in open-access papers (continued):
Sharing a sentence is not in itself a finding about the gene and the disease.
tumor (continued). "Acetazolamide, carbonic anhydrase inhibitor, used in glaucoma to reduce aqueous humor production, have been shown as irreversible inhibitor of AQP1 and 4 which protected tumor from cytotoxic edema and promoted tumor metastasis in glioma." (PMID 33796134, 2021). "In the present study, we made further progress by demonstrating that RIPK1, a cell death regulator, is the key mediator of AQP1-initiated pro-tumor signaling involved in the pathophysiological process of TNBC." (PMID 33980862, 2021). "In this field, some previous studies highlighted the potential role in carcinogenesis, tumor progression and metastasis development of different cancers by Aquaporin 1 (AQP1), a small trans-membrane water channel protein." (PMID 33807998, 2021). "Taking into consideration a cut-off of ≥ 1 % positive tumor cells, 20 (62.5%) cases showed positive AQP1 staining (AQP1+), while 12 (37.5%) cases were considered negative (AQP1–)." (PMID 33807998, 2021). "Meanwhile, in patient 1, tumor piece 2 pronouncedly high AQP1 expression correlates with high CXCR4 and HIF expression, in patient 3, a higher or lower AQP1 expression does not correlate with CXCR4 expression." (PMID 33467498, 2021). "Previous studies have identified Aquaporin 1 (AQP1), a water-transporting transmembrane protein, to be upregulated in TNBC and associated with the tumor development and progression." (PMID 33980862, 2021). "Studies show that AQP-1 promotes tumor progression, and its blockade curtailed the migration and tube formation of ECs." (PMID 34681190, 2021). "Acetazolamide reduced angiogenesis, tumor growth, and tumor invasion in the Lewis lung carcinoma mouse model, effects consistent with possible AQP1 downregulation, although other contributing mechanisms of action need to be considered." (PMID 33499000, 2021). "The angiogenesis cluster—besides containing some of the same previous ECM proteins—comprised the angiopoietin ANGPTL4 and other genes that are known to act in tumour-induced angiogenesis (AQP1, RAMP1, HSPB1, MYLK), for a total of 21 entries." (PMID 34439343, 2021). "Reduced levels of AQP1 in vitro by small interfering RNA and in vivo by genetic knockdown led to decreased angiogenesis and corresponding reductions in tumor growth and invasiveness." (PMID 33499000, 2021). "Recently, the resistance to programmed cell death, including apoptosis and necroptosis, has been identified by emerging evidence as a putative mechanism of cytoplasmic AQP1-driven tumor proliferation and cancer spread." (PMID 33980862, 2021). "The result demonstrated that TNBC patients with high tumor expression had less favorable survival compared with patients, whose tumors expressed a low level of AQP1 (hazard ratio, 3.76; p = 0.03)." (PMID 33980862, 2021). "Genetic inhibition of RIPK1 significantly exacerbated the pro-tumor effect of AQP1, while ectopic expression of RIPK1 notably blunted AQP1 signaling." (PMID 33980862, 2021). "Targeting AQP1 is emerging as a strategy of interest to reduce angiogenesis and tumor growth across a wide range of cancer types." (PMID 33499000, 2021). "AQP1 in vascular endothelial cells also showed a positive correlation with tumor growth, histologic grade, and extra-uterine metastases, suggesting a parallel role for angiogenesis in aiding tumor growth and spread." (PMID 33499000, 2021). "An imaging parameter which can reflect the AQP1 expression will be a useful marker in clinical application, especially in response prediction and tumor surveillance." (PMID 32576929, 2020). "Upregulation of AQP1 occurs predominantly in the perivascular space that is distant from the necrotic tumor core and has high tumor infiltration." (PMID 32253832, 2020). "Depending on the type of disease, the ratio of AQP1 expression to intra-tumor microvessels was the highest in adenocarcinoma." (PMID 33271827, 2020).
tumor (continued). "AQP1 knockout mice showed low angiogenesis in the cancer tissue resulting in subcutaneously induced melanoma tumor necrosis in these mice." (PMID 33271827, 2020). "Upregulation of Kv11.1 expression was associated with advanced tumor grade and high expression of Ki67 proliferative marker, whereas TRPV6, TRPM8 and AQP1/AQP3 channels were positively correlated with tumor stages III and IV and large tumor size." (PMID 33178018, 2020). "Accumulating research has found that AQP1 can affect multiple important biological processes, including angiogenesis, wound healing, tumor metastasis, and invasion, etc.." (PMID 32903818, 2020). "AQP1-mediated rapid transmembrane transport of water flux is one of the important mechanisms to promote tumor cell migration." (PMID 32903818, 2020). "Conversely, the mRNA and protein of AQP1 in BC tissues and cell lines are significantly higher than those in the adjacent non-tumor tissues and MCF-10A cells." (PMID 32903818, 2020). "AQP1 expression was especially high in the perivascular foci within the boundary of the normal brain and the tumor tissue." (PMID 32253832, 2020). "Other studies have demonstrated that tumor angiogenesis in AQP1 knockout mice after tumor xenograft was clearly inhibited." (PMID 33271827, 2020). "And in a long-term follow-up, AQP1 expression in 203 patients with aggressive BC shows a significant correlation with high tumor grade, medullary-like histology, and “triple-negativity”." (PMID 32903818, 2020). "AQP1 is involved in tumor malignancy by facilitating the migration and invasion of GBM cells, and promoting the formation of vascular beds that are characteristic of GBM by downregulating THSD7A." (PMID 32253832, 2020). "The observation of a significantly decreased AQP-1 expression, similar to the observed in HBs, would lead to slowing down of the cystic growth surrounding the tumor." (PMID 32854260, 2020). "The results of studies on the expression of AQP1 in vascular endothelial cells indicate a key role of AQP1 in tumor angiogenesis by accelerating the migration of cancer cells." (PMID 33271827, 2020). "In adenocarcinoma and endometrial hyperplasia, AQP1 was localized in the microvascular epithelium and small vessels of the tumor." (PMID 33271827, 2020). "In all the specimens at least 5%‐50% of the GBM cells expressed AQP1, and 50% to >75% of tumor cells expressing AQP1 (> grade 3) are found to be the majority of the specimens (29/33, approximately 88%)." (PMID 32253832, 2020). "Regulation of the enzyme carbonic anhydrase IX as well as probably AQP1 by HIF-1α furthers tumor progression and poorer survival in several other solid tumors." (PMID 31600976, 2019). "Impaired tumor growth in AQP1-null mice, including a reduced tumor vascularity and extensive tumor necrosis, but an enhanced survival of tumor-bearing mice was observed." (PMID 31023968, 2019). "Tumor tissue was examined using immuno-histochemical analysis of AQP1 and CAIX and treatment response assessment using isothermal microcalorimetry of tissue slice cultures." (PMID 31600976, 2019). "ZNF154 and AQP1, whose hypermethylated patterns are biomarkers for distinguishing tumor from normal samples, are downregulated and hypermethylated in BRCA and LUAD in our study." (PMID 31828117, 2019). "AqB013 and AqB050 compounds inhibit aquaporin 1 (AQP1), a dual water and ion channel implicated in tumour angiogenesis." (PMID 31013775, 2019). "Since DW-MRI showed significant changes depending on the state of the tumor after IR, we also analyzed two major aquaporins (AQPs), AQP1 and AQP4, which are transmembrane water transporters that are primarily expressed in the brain tissue." (PMID 31803626, 2019). "In humans, AQP1 is abundantly expressed in the endothelium of many tissues including the endothelium of tumor micro-vasculature, positive for CD31." (PMID 30678106, 2019).
tumor (continued). "Most findings support a fundamental role of AQP1 in cell migration, which is central to diverse biological phenomena including angiogenesis, wound healing, organ regeneration, and tumor spreading." (PMID 31023968, 2019). "AQP1 is believed to play a role in the endothelial cell migration process that promotes tumor angiogenesis." (PMID 30555637, 2018). "In conclusion, this study shows that AQP1 is not only able to promote tumour angiogenesis but it can also facilitate tumour cell intravasation and metastatic formation, probably promoting an increase in endothelial permeability." (PMID 29044946, 2018). "In recent years, other important biological effects of AQP1 have also been discovered, including its ability to promote cell migration, wound healing, tumour growth and metastasis and CO2 transport across the cell membrane." (PMID 29554889, 2018). "Recent studies have described important roles for AQP1 in epithelial carcinogenesis and tumor behavior." (PMID 30042826, 2018). "Immunofluorescence experiments performed on tumour cryosections showed a significantly higher CASP3 staining for AQP1 siRNA‐treated compared to CTRL siRNA‐treated tumours as confirmed by fluorescence intensity analysis quantification." (PMID 29044946, 2018). "Tumor mass, vessel density, and lung metastasis were found to be lower when compared to mice with normal AQP1 levels." (PMID 30555637, 2018). "In conclusion, these findings highlight an additional role for AQP1 as an important determinant of tumour dissemination by facilitating tumour cell extravasation and metastatic formation." (PMID 29044946, 2018). "We believe this study adds knowledge on the intricate role of AQP1 at the vascular level and in tumour biology, which is key in view of potential alternatives to the current antiangiogenic therapy mainly based on VEGF pathways." (PMID 29044946, 2018). "More importantly, reduced AQP1‐dependent endothelial permeability would also be an obstacle for tumour cells to escape the tumour and disseminate to form metastasis." (PMID 29044946, 2018). "On the other hand, our results suggested that ESCC cells in which AQP1 is expressed predominantly in the cytoplasm and plays a crucial role in tumor progression." (PMID 30042826, 2018). "of SCC, tumor size, lymphatic invasion, venous invasion, pT and pN categories, and AQP1 expression) influenced prognosis." (PMID 30042826, 2018). "The immunohistochemical overexpression of AQP1 was defined as ≥50% of tumor cells showing membranous staining." (PMID 29495596, 2018). "For example, targeted disruption of AQP1 reduced migration of aortic endothelial cells and limited tumor angiogenesis and growth." (PMID 29769447, 2018). "Immunohistochemistry for the AQP1 protein was performed to investigate the expression of AQP1 in primary tumor tissues of 50 human ESCC samples." (PMID 30042826, 2018). "Starting from day 0, tumours were measured every 3 days to monitor tumour growth that, in line with previous experiments, was found significantly reduced in AQP1 siRNA compared with CTRL siRNA and untreated mice." (PMID 29044946, 2018). "This study adds knowledge on the role played by AQP1 in tumour biology and supports the view of AQP1 as a potential drug target for cancer therapy." (PMID 29044946, 2018). "As MMP2 is normally produced by resident tumour cells, the reduced amount of MMP2 found in AQP1 siRNA‐treated tumours is first of all the consequence of the reduced number of tumour cells." (PMID 29044946, 2018). "In particular, AQP1 deletion diminishes endothelial cell migration, limiting tumor angiogenesis and growth, on the other hand, AQP1-expressing tumor cells have enhanced local infiltration and metastatic effects." (PMID 29503618, 2018). "Results revealed a reduced expression of MMP2 in AQP1 siRNA‐treated tumours compared to CTRLs, indicating that reduced AQP1‐dependent vascularization is also cause of MMP2 reduced expression." (PMID 29044946, 2018).
tumor (continued). "Increased AQP1 in tumor cells has shown to enhance metastatic potential and raise local infiltration." (PMID 29678898, 2018). "This means that although under hypoxic condition VEGF is produced in AQP1 siRNA‐treated tumours, it remains trapped in the extracellular matrix (ECM), therefore reducing its effect in promoting angiogenesis." (PMID 29044946, 2018). "The aim of this study was to investigate the potential role of AQP1 in VM of MM cell lines and primary cells under normoxic and hypoxic conditions to mimic the tumour microenvironment." (PMID 29104239, 2017). "There have been two articles published in which expression of TGF-β was examined in AQP1 down-regulated tumour cells." (PMID 28146084, 2017). "Growing evidence supports its involvement in the development and progression of many types of cancer through AQP1-facilitated tumour cell migration, invasion, angiogenesis and possibly through tumour cell proliferation." (PMID 28146084, 2017). "Available literature implicates the role of AQP1 in tumour cell migration, invasion and angiogenesis." (PMID 28146084, 2017). "In comparison to tumour cell migration and tumour angiogenesis, the evidence for AQP1-facilitated tumour cell proliferation is less substantial." (PMID 28146084, 2017). "This article reviews the current understanding of AQP1-facilitated tumour development and progression with a focus on regulatory mechanisms and downstream signalling pathways." (PMID 28146084, 2017). "This implied that AQP1 facilitated the migration not only of tumour cells but also endothelial cells, enabling tumour angiogenesis." (PMID 28146084, 2017). "C-Myc, often up-regulated in tumour cells is known for its ability to directly stimulate the transcription of E-Box-containing genes thus up-regulating AQP1 expression." (PMID 28146084, 2017). "Because tumor cells with high levels of AQP1 had a stronger capacity for cell migration, invasion, and metastasis, the BM-MSC-CM effect on wound healing was investigated." (PMID 27409610, 2016). "Proliferating microvessels of malignant tumors have been shown to highly express AQP1, as well as some tumor cells." (PMID 28036023, 2016). "Using the 2-ΔΔCt relative quantification method, AQP1 was over-expressed (by >1.6-fold) in 22/57 (39 %) colon tumours compared to matched normal mucosa." (PMID 26912239, 2016). "The results showed that the AQP1 level was increased in both tumor cell lines after treatment with BM-MSC conditioned medium." (PMID 27409610, 2016). "Median patient survivals for patients with <50% (n = 47) and ≥50% (n = 44) tumour cells expressing AQP1 were 13 (95% CI 7.9–18) and 8 (95% CI 4–12) months respectively, using the Kaplan Meier method." (PMID 27376267, 2016). "4.8% (10/207) patients in the low AQP1 expression group died of tumor; while 14.5% (17/117) patients in the high expression group suffered tumor-related death." (PMID 26812884, 2016). "Colon tumour cells over-expressing AQP1 exhibited increased migratory and invasive capacity in wound healing (migration) and transwell invasion assays." (PMID 26912239, 2016). "For example, AQP1 is overexpressed in tumor microvessels, and this correlates with higher metastatic potential and aggressiveness of the malignancy." (PMID 27023529, 2016). "AQP1 over-expression in mice increased the extravasation of tumour cells injected via the tail vein compared to control mice, and increased by 3-fold the number of lung metastases." (PMID 26912239, 2016). "The range in staining for AQP1 concurs with the range of expression levels in tumour tissue at the mRNA level." (PMID 26912239, 2016). "We characterize the imaging performance and mechanisms of AQP1 through live-cell experiments and Monte Carlo models, and demonstrate its utility by imaging tumour gene expression in vivo." (PMID 28008959, 2016). "In particular, many studies showed a key role of AQP1 in metastatic process and neo-angiogenesis in a tumor animal model." (PMID 27409610, 2016).
tumor (continued). "AQP1 is abnormally expressed in tumor endothelial cells, whereas AQP1 deletion in knockout mice greatly impaired tumor growth, angiogenesis and cell migration." (PMID 27023529, 2016). "It was reported that vascular endothelial cells expressed AQP1 to play a key role in the pathogenesis of tumor angiogenesis by accelerating cells migration." (PMID 25886458, 2015). "The over-expression of AQP1 was predominantly located in perivascular areas or areas of tumor cell infiltration, distant from the necrotic tumour core." (PMID 25886458, 2015). "It suggested that AQP1 expression was strongly correlated with tumor angiogenesis and proposed as a therapeutic target in brain cancer." (PMID 25886458, 2015). "Studies in AQP-1 null mice revealed impaired tumor angiogenesis and endothelial cell migration, which was ascribed to a decreased water influx that impairs the formation of lamellipodia at the leading edge of migrating cells." (PMID 26717516, 2015). "AQP1-null mice had low ability to form the angiogenesis in the cancer tissue induced by subcutaneous injection of melanoma cells and produced extensive tumor necrosis." (PMID 25886458, 2015). "AQP1 can combine with carbonic anhydrases to shut H+ from the intracellular to the extracellular compartment, leading to prevention from tumor cytotoxic edema and acidification of extracellular compartment." (PMID 25886458, 2015). "In AQP1-knockout mice, xenograft tumor growth and angiogenesis were reduced, and significant necrosis occurred in the tumor tissues." (PMID 24918928, 2014). "In this study, MVD was used to assess the expression of AQP1 protein, as it was localized to the tumor microvessels." (PMID 24918928, 2014). "AQP-expressing cancer cells show enhanced migration in vitro and greater local tumor invasion, tumor cell extravasation, and metastases in vivo than AQP1-null transgenic mice." (PMID 24338153, 2014). "AQP1 expression was seen in 11 tumors (5.4 %) and showed a highly significant correlation with high tumor grade, medullary-like histology, “triple-negativity”, cytokeratin 14 and smooth muscle actin expression." (PMID 24338153, 2014). "Our results also showed high expression of AQP1 in the small blood vessels surrounding the tumor, suggesting an important role of AQP1 in tumor angiogenesis." (PMID 24917931, 2014). "Using such an approach, we were unable to find significant differences in both AQP1 and AQP5 expression according to the underlying neoplasm." (PMID 24917931, 2014). "AQP1-null mice display reduced tumor growth after subcutaneous implantation of melanoma cells, which is associated with reduced endothelial cell migration and angiogenesis." (PMID 23017148, 2012). "Only little is known about the expression of AQPs in NSCLCs: AQP1 is expressed in AC and it was shown that AQP1 expression facilitated tumor cell migration and spread whereas AQP1 inhibition reduced the metastatic potential of tumor cells." (PMID 21548930, 2011). "In the case of poorly oxygenated tumors, an increment of Aqp1 expression in the vicinity would explain the typical edematous area surrounding the tumor." (PMID 22174795, 2011). "AQP1, -3, -4, -5 and -9 were differentially expressed between tumor and normal or AC and SCC subtype in at least one microarray dataset (p-value < 0.05; Fold change ≥ 2 or ≤ 0.5), and therefore selected for further qRT-PCR analysis." (PMID 21548930, 2011). "Only in one case was there communicating hydrocephalus and this patient's tumour had strong AQP1 staining." (PMID 20860832, 2010). "The involvement of AQPs in cell migration was uncovered based on the observation that tumour angiogenesis was impaired in AQP1-null mice and upon subsequent characterization of endothelial cell cultures from wild-type and AQP1-null mice." (PMID 21119881, 2010). "Overexpression of AQP1 has been reported in proliferating tumor vessels suggesting its involvement in tumor angiogenesis." (PMID 20806077, 2010).